CD69 (CD69 molecule)
Diseases named in the same sentence as CD69 in open-access papers (continued):
Sharing a sentence is not in itself a finding about the gene and the disease.
Glucose intolerance (2 papers, 2019 to 2023). Glucose intolerance (GI) can be defined as dysglycemia that comprises both prediabetes and diabetes. "Expression of CD69 on total CD4+ T cells rose with progressive glucose intolerance (p = 0.004), which was robust to adjustment for BMI (p = 0.03 for metabolic status) and to age (p = 0.01 for metabolic status) in separate models (data not shown)." (PMID 30941121, 2019). "Given the stepwise progression of CD69 expression on CD4+ T cell subsets with rising glucose intolerance, and the significant pairwise comparisons, a linear regression model was used to assess CD69 expression according to metabolic status." (PMID 30941121, 2019). "We confirmed with flow cytometry that participants with glucose intolerance had higher proportion of CD4+ CD69+ T cells (median percent: non-diabetic (6.4%), prediabetic (37.5%), diabetic (37.7%); p < 0.05 for both), which is consistent with prior studies." (PMID 37711619, 2023). "The proportions of SAT CD4+ and CD8+ memory subsets were similar across metabolic status categories in the PLWH, but CD4+ T cell expression of the CD69 early-activation and tissue residence marker, particularly on TEM cells, increased with progressive glucose intolerance." (PMID 30941121, 2019). "Our study design precludes an assessment of whether the presence of increased CD69+ TEM and TEMRA cells preceded or followed the development of glucose intolerance, though future longitudinal studies in PLWH with early indications of metabolic disease could address this question." (PMID 30941121, 2019). "While we observed the relative proportions of SAT CD4+ and CD8+ TCM, TEM, and TEMRA cells to be similar regardless of metabolic status in PLWH, expression of CD69 on CD4+ T cells rose with progressive glucose intolerance in a step-wise progression from non-diabetic, to pre-diabetic, to diabetic." (PMID 30941121, 2019).
HCMV infection (2 papers, 2018 to 2023). "When % CD69+ was used to assess MAIT cell activation all significance was lost, suggesting that in this assay set up both HCMV infection and the MR1 neutralizing antibody were affecting the degree of activation more significantly than the proportion of activated MAIT cells." (PMID 36845106, 2023).
head and neck cancer (2 papers, 2022 to 2024). A primary or metastatic malignant neoplasm affecting the head and neck. "The protein level of exosomal PDL1 derived from head and neck cancer cells is significantly associated with disease progression, number of tumor nodules, and tumor stage, which may downregulate CD69 antigen level of cytotoxic T cells and reduce CD8+ T cell activity." (PMID 39421264, 2024).
Hepatic steatosis (2 papers, 2021 to 2024). Steatosis is a term used to denote lipid accumulation within hepatocytes. "This altered permeability is associated with the degree of hepatic steatosis and could be responsible for the increased CD69+ activation of iNKT cells." (PMID 35052736, 2021). "The clinical benefits of these short-term changes require further exploration; however, long-term dietary restriction in patients with non-alcoholic fatty liver disease resulted in a decrease in intrahepatic MAIT CD69 expression and improvements in inflammatory-mediated hepatic steatosis." (PMID 38674935, 2024).
infertile (2 papers, 2019). "The results showed that 15.8% ± 5.9 of total CD56 cellsin patients with RPL and 32% ± 14.4 in the infertile groupexpressed CD69 as compared with 10.6% ± 5.01 in controlgroup." (PMID 30644239, 2019). "There was a statistically significant difference in theexpression of CD69 in CD56+ cells between the controlgroup and RPL group (P=0.001), the infertile group(P=0.001) and between RPL and infertile group (P=0.001)." (PMID 30644239, 2019). "An increased percentage of CD56+NK cells in patients with unexplained infertility, an elevated expressionof CD69 on NK cells in patients with RPL and infertility and a high level of perforin on CD56+cells in the RPL groupmight be considered as immunological risk factors in these women." (PMID 30644239, 2019). "Moreover, there wasa significant increase in the display of CD69 on CD56+cells in the RPL group and the infertile group comparedwith the control group." (PMID 30644239, 2019). "Furthermore, the levels of CD69 and IFN-γ were significantly decreased and the level of PD-1 was increased in both CD4+ and CD8+ T cells from infertile patients with PCOS (P < 0.05)." (PMID 30988342, 2019). "Although the percentage of CD4+ T cells did not change in PCOS patients with infertility, both CD4+ and CD8+ T cells expressed significantly lower levels of CD69 in the PCOS group (P < 0.01)." (PMID 30988342, 2019).
ischemic stroke (2 papers, 2019 to 2023). A stroke disorder caused by obstruction of blood flow to the brain, due to thrombotic (local blood clot formation) or embolic (due to a blood clot or other material traveling from another site) event. "Low expression of cluster of differentiation 69 (CD69) was found to propagate enhanced inflammatory responses and worsen brain damage after ischemic stroke in animal models through immune cells." (PMID 37373979, 2023).
kidney transplant (2 papers, 2019 to 2024). A surgical procedure in which one or both kidneys from a donor are implanted into a recipient. "(b) Flow cytometry analysis of single-cell suspension liver metastasis, comparing treatment of UM22 TILs and UM22 MART1-specific TILs for CD3+, CD3+CD8+CD69+, or CD3+CD8+CD137+." (PMID 39312285, 2024).
laryngeal carcinoma (2 papers, 2022 to 2024). Carcinoma that arises from the laryngeal epithelium. "As for the study group, which included laryngeal cancer patients and their division into EBV+ and EBV- patients, statistical significance was observed only in the case of CD19+CD69+ B-lymphocytes in the blood, as well as CD4+PD-1." (PMID 38256645, 2024). "The last comparison group was patients with EBV-laryngeal cancer versus a group of healthy EBV volunteers, in which we observed a lack of statistical significance only in the population of CD19+CD69+ B lymphocytes, as well as in the IgG VCA EBV quantitative group." (PMID 38256645, 2024).
leishmaniasis (2 papers, 2018 to 2024). Infectious disease that is transmitted through the bite of hematophagous female phlebotomine sand flies. "In experimental leishmaniasis, lesions harbor both CD4+ T cells that lack CD69 expression presumably in traveling through the tissues and a separate group of resident T cells expressing the CD69 marker." (PMID 38469319, 2024). "Although the CD69 marker has been assessed as an activation marker in CD4+ and CD8+ T-cell compartments in blood and skin lesion of human leishmaniasis patients, insufficient data are available regarding the involvement of TRM cells in human leishmaniasis." (PMID 38469319, 2024). "When peripheral blood mononuclear cells or purified NK cells and monocytes (all derived from healthy blood donors from Germany without a history of leishmaniasis) were exposed to promastigotes, NK cells showed increased surface expression of the activation marker CD69." (PMID 29472914, 2018). "Upregulation of CD69 is a first sign of NK cell activation but does not automatically entail the production of IFN-γ required for parasite control in mouse and human leishmaniasis." (PMID 29472914, 2018).
Listeria infection (2 papers, 2015 to 2016). "CD69 has been shown to prevent immunopathology caused by Listeria monocytogenes infection." (PMID 27721814, 2016). "While nearly 40% of T cells and 60% of B cells were positive for CD69 surface expression in WT mice 24 h after Listeria infection, dramatically fewer CD69+ lymphocytes were found in Hvem-/- mice." (PMID 26245828, 2015).
lung adenocarcinoma (2 papers, 2018 to 2022). A carcinoma that arises from the lung and is characterized by the presence of malignant glandular epithelial cells. "The authors also observed that CXCL12 correlated with a higher degree of tumor inflammation and suggested that the concomitant presence of activated TILs CD4+CXCR4+ CD69+ might influence tumor progression by shaping the immune cell population infiltrating lung adenocarcinomas." (PMID 35740564, 2022).
lung squamous cell carcinoma (2 papers, 2015 to 2023). "However, significantly elevated ratios of activated CD69+/CD94+ NK cells that are associated with low serum Hsp70 levels were observed only in patients with squamous cell lung cancer." (PMID 26579130, 2015).
metastatic melanoma (2 papers, 2020 to 2022). A melanoma that has spread from its primary site to another anatomic site. "Also, according to a retrospective study of metastatic melanoma, an increased proportion of CD8-positive cells with elevated PD-1 and CD69 expression was observed while on chemotherapy as compared with all-time points on ICIs, suggesting immune-activation by interaction of chemotherapy and ICIs." (PMID 33117701, 2020).
metastatic tumor (2 papers, 2021 to 2024). "In agreement with our in vitro finding, administration of CFTRi significantly reduced Arg1 expression levels in MoMs, increased CD8+ T cell infiltration and their activation (GzmB+CD8+; CD69+CD8+ T cells) in early metastatic tumors." (PMID 38355776, 2024).
Neonatal sepsis (2 papers, 2012 to 2025). Systemic inflammatory response to infection in newborn babies. "Infection drives immune cell activation by increasing expression of cell surface receptors and cell surface markers, including CD64 on neutrophils and CD69 on NK cells, which have been indicated as potential biomarkers for early diagnosis of neonatal sepsis." (PMID 39978117, 2025).
pemphigus (2 papers, 2017 to 2023). Pemphigus is a group of rare autoimmune diseases that cause blistering of the skin and mucous membranes (mouth, nose, throat, eyes, and genitals).This conditioncan occur at any age, but often strikes people in middle or older age. "The study demonstrated that skin‐infiltrating CD4+CD69+CCR7− Trm was more prevalent in pemphigus patients than in healthy controls and was positively correlated with the pemphigus disease area index." (PMID 36539957, 2023).
periodontal disease (2 papers, 2021 to 2024). "NK and CD8 + T cells within the oral blood mononuclear cells (OBMCs) expressed significantly higher levels of CD69 in patients with periodontal disease compared to those from healthy controls." (PMID 33672708, 2021).
plaque psoriasis (2 papers, 2018 to 2021). "But the expression of genes in this pathway of small plaque psoriasis is significantly higher than that of large plaque psoriasis, and negative immune regulators like CD69 and FAS have been found to be down-regulated in large plaque psoriasis." (PMID 29515135, 2018). "Moreover, in an immunohistochemical study of skin lesions in patients with plaque psoriasis, we found a significant increase in the immunoreactive area of CD69 in the epidermis (25.24 ± 1.42%), but these values did not change in the dermis (7.94 ± 1.13%)." (PMID 34769769, 2021).
pneumococcal infection (2 papers, 2020 to 2024). Infections with bacteria of the species streptococcus pneumoniae. "However, studies in lungs after Bordetella pertussis and Streptococcus pneumonia infection showed that tissue resident memory γδT cells expressed CD69 and some co-expressed CD103, supporting the conclusion that CD69 and/or CD103 expression were also surface markers of tissue resident γδT cells." (PMID 33519808, 2020).
respiratory syncytial virus infection (2 papers, 2016 to 2025). "Following respiratory syncytial virus infection, only CD11c+ CD8+ T cells show signs of recent activation, including up-regulation of CD11b/CD69, and are recruited preferentially to the lung." (PMID 27119555, 2016).
rheumatic disease (2 papers, 2021 to 2023). "CD21lo B cells isolated from rheumatic disease patients upregulate costimulatory molecules and drive CD69 upregulation on T cells, suggesting CD21lo B cells are competent to present antigen to T cells." (PMID 33468230, 2021). "The high-dimensional immune profiling study presented here deeply phenotyped in parallel synovial CD8+ and CD4+ CD69+CD103+ TRM cells in two rheumatic diseases and identified them as a heterogeneous population characterized by multiple distinct phenotypes and functions." (PMID 37195862, 2023).
Salmonella Infections (2 papers, 2010 to 2023). Infections with bacteria of the genus SALMONELLA. "In the same respect, CD4+CD69+ T cells expressing a high level of P2X7 have previously been characterized as TRMs that are key factors in promoting protection against the severe effects of Salmonella infection." (PMID 37457702, 2023). "Given the durability whereby T cells maintain changes in CD44 and CD62L expression, and IFN-γ production after activation, the expression of more transient T cell activation markers such as CD25 and CD69 were also quantified throughout persistent Salmonella infection." (PMID 20714351, 2010). "Thus, the sharp increase in T cell activation that occurs between weeks 3 and 4 after Salmonella infection is confirmed using both transient (CD25, CD69) and more stable (CD44, CD62L, IFN-γ) markers of T cell activation." (PMID 20714351, 2010).
sarcoidosis (2 papers, 2019 to 2023). Sarcoidosis is a multisystemic disorder of unknown cause characterized by the formation of immune granulomas in involved organs. "To clarify the associations between MAIT cell activity and sarcoidosis disease activity, we analyzed correlations between the expression levels of CD69 on MAIT cells and clinical variables." (PMID 31515495, 2019). "The peripheral blood of sarcoidosis patients also showed higher expression levels of CD69 and PD-1 on MAIT cells compared with healthy controls." (PMID 31515495, 2019). "Furthermore, we compared CD69 expression levels on MAIT cells in peripheral blood with BALF from sarcoidosis patients." (PMID 31515495, 2019). "Similarly, we found that CD69 expression on MAIT cells was much higher in sarcoidosis patients than in healthy controls and was significantly correlated with the clinical biomarkers ACE and sIL-2R." (PMID 31515495, 2019). "In addition, the level of CD69 expression on MAIT cells was positively correlated with the IL-18 concentration in the serum of sarcoidosis patients (r = 0.431, P = 0.01)." (PMID 31515495, 2019). "Similarly, in the present study, serum IL-18 levels were significantly higher in sarcoidosis patients than in healthy controls, and we observed a significant correlation between the serum IL-18 concentration and CD69 expression level on MAIT cells in peripheral blood." (PMID 31515495, 2019). "EVs from IPF patients expressed CD56 primarily in the alveolar compartment, even if CD69 expression was lower in IPF than HP and sarcoidosis BAL samples." (PMID 36835481, 2023). "In peripheral blood, the proportion of MAIT cells was lower (P = 0.0002), but the expression levels of CD69 and programmed death 1 on MAIT cells were higher in sarcoidosis patients than in healthy controls." (PMID 31515495, 2019). "CD69 expression levels were significantly correlated with ACE and sIL-2R levels, which are markers of clinical sarcoidosis disease activation." (PMID 31515495, 2019). "The proportions of CD69+ MAIT cells and PD-1+ MAIT cells among all MAIT cells were significantly higher in sarcoidosis patients (P = 0.01 and P = 0.02, respectively)." (PMID 31515495, 2019).
sialadenitis (2 papers, 2021 to 2024). Sialadenitis is an infection of the salivary glands. "In both ESS mouse models and patients with pSS, tissue-specific CD8+CD103+CD69+ TRM was identified as being involved in sialadenitis, with a significant increase in IFN-γ production, in which CD69 and CD103 are the tissue residence markers." (PMID 39469708, 2024). "Moreover, RORγ-transgenic mice, an established SS-like sialadenitis mice model, were reported to induce the expression of IL-2-mediated CD25 and CD69 on CD4+ T cells." (PMID 33726818, 2021).
silicosis (2 papers, 2021 to 2024). Silicosis is a respiratory disease caused by breathing in (inhaling) silica dust. "In synthesis, these results demonstrated that CD4+ TRM cells exerted immuno-memory to the CS particles mediated the pathogenesis of silicosis, and the CD69+CD103– TRM subsets possessed robust pathogenic capacity to silicosis." (PMID 39122899, 2024). "Analogous to the immuno-suppressive CD69+CD103+ Tregs in silicosis, CD69+ Tregs protect from inflammatory damage after myocardial infarction." (PMID 39122899, 2024). "After identifying pathogenic CD69+CD103- subsets, we highlight IL-7 for their maintenance and function, that present a promising avenue for mitigating silicosis." (PMID 39122899, 2024). "Remarkably, the ratio of CD103+ to CD103– in CD69+CD4+ TRM cells was lifted with silicosis progression, emphasizing the immune imbalance within TRM subsets would be related to fibrogenesis." (PMID 39122899, 2024). "With the expansion of CD4+ TRM cells, there was an increasing number of CD69+CD103+ and CD69+CD103– subsets, implying their pathogenic roles in silicosis." (PMID 39122899, 2024). "The percentage of CD69+CD8+ T cells in PB was significantly increased in the asbestosis group compared to the healthy control group (P < 0.05), and the percentage of CD69+CD8+ T cells tended to be higher in the silicosis group than in the healthy control group." (PMID 34022844, 2021). "Thus, modulating immuno-balance within CD4+ TRM cells that restrained the number and function of CD69+CD103− TRM subsets may provide therapeutic effects in treating silicosis." (PMID 39122899, 2024). "In synopsis, we proved the cell retention markers CD103 and CD69 can define CD4+ TRM cells into functional distinct lineages, which may provide potential therapeutic targets for alleviating silicosis." (PMID 39122899, 2024). "The CS-stimulated pulmonary CD4+ TRM cells expressed CD69, regardless of Teff cells or Tregs, implying a crucial role of this molecule in silicosis." (PMID 39122899, 2024).
vasculitis (2 papers, 2014 to 2022). "Since activated platelets release Myl9, it has been suggested that the CD69-Myl9 system is involved in various inflammatory diseases, including vasculitis." (PMID 36685558, 2022). "Thus, our results indicate a possible involvement of the CD69-Myl9 system in the pathogenesis of KD vasculitis, although further experiments are required to show the functional contribution of this system to KD vasculitis." (PMID 36685558, 2022). "Markers such as CD69 that represent early activation of lymphocytes are not up-regulated in the HCV MC vasculitis group, suggesting a distinct pattern of immune activation in HCV MC patients than that observed with HIV/HCV coinfected subjects." (PMID 24904592, 2014).
acne (1 paper, 2021). An inflammatory process of the sebaceous glands which is characterized by comedones, nodules, papules and/or pustules on the skin. "This point is reinforced by CD69 expression on the mast cell surface in UI skin as well as during the CC and PA stages, suggesting that these cells are implicated very early in acne." (PMID 34650562, 2021). "Taken together, these results indicate that CD161+ and CXCR3+ Th cells dominate in acne skin and that these cells reside in UI skin as CD69+ T cells." (PMID 34650562, 2021). "The fact that CD69+ absolute cell number increased (for both CD4+ and CD8+ T cells) at the CC stage and plateaued at the PA stage (a non-significant slight decrease was measured) suggests that these TRM cells might be involved and proliferate in the very early steps of acne pathogenesis." (PMID 34650562, 2021).
acute coronary syndrome (1 paper, 2025). Signs and symptoms related to acute ischemia of the myocardium secondary to coronary artery disease. "Furthermore, in patients with acute coronary syndrome (ACS), the proportion of CD8+CD69+CD137+ cells was significantly increased in peripheral blood mononuclear cells (PBMC) after activation by the autoantigen LL-37." (PMID 40599317, 2025).